HIF1A (hypoxia inducible factor 1 subunit alpha)
Diseases named in the same sentence as HIF1A in open-access papers (continued):
Sharing a sentence is not in itself a finding about the gene and the disease.
liver fibrosis (continued). "Tissue hypoxia was observed in the liver and HIF-1α expression was enhanced in animals with decompensated-stage heart failure, in which cardiac output decreased, suggesting that tissue hypoxia contributes to hepatic fibrosis." (PMID 26863419, 2016). "The research performed in Schistosomajaponicum infection animal illustrated that Hif-1α is activated in liver infection and might be an important regulatory factor in liver fibrosis." (PMID 24040163, 2013). "Despite of recent rapid advance in understanding the interactions between various pathways contributing to regulate Hif-1α, the links in regulating Hif-1α activity of liver fibrosis remain to be answered, since Hif-1α activity was proposed to be tissue specific." (PMID 24040163, 2013). "In this study, we aimed at exploring the function of Hif-1α in activation of hepatic stellate cells, which plays a key role in pathogenesis of liver fibrosis, and also the relationship of MAPK signaling pathway with Hif-1α-regulated signaling cascades in hepatic stellate cells." (PMID 24040163, 2013). "Furthermore, although STING deficiency led to decreased HIF-1α expression, further investigation is needed to establish whether HIF-1α is an indispensable downstream mediator of STING signaling in hepatic fibrosis." (PMID 41208891, 2025). "HIF-1α is a critical regulator of cellular and systemic responses to low oxygen levels, and hepatocyte hypoxia contributes directly to the progression of liver fibrosis; therefore, we hypothesized that HIF-1α could play an important role in PCSK9 expression and autophagy during liver fibrosis." (PMID 37466835, 2023). "Several studies have shown that hypoxia-inducible factor-1α (HIF1A) is critical for upregulation of pro-fibrotic mediators, such as platelet-derived growth factor A/B, and plasminogen activator inhibitor-1 (SERPINE1), and mice deficient in HIF1A had reduced liver fibrosis." (PMID 34301291, 2021). "Taken together, these findings suggest that CTS might play a contributory role in the progression of liver fibrosis by augmenting the biosynthesis of cholesterol that, in turn, activates HSCs, redox, oxidant stress, inflammatory, and, HIF-1α pathways during chronic liver disease." (PMID 32635162, 2020). "Therefore, we examined the expression of HIF-1α in liver fibrosis." (PMID 32637414, 2020). "Therefore, a pharmaceutical strategy for liver fibrosis involving inhibition of the level of HIF-1α may be beneficial for patients with liver disease." (PMID 31455001, 2019). "However, chronic activation of HIF-1α and iNOS can result in liver fibrosis and liver damage." (PMID 29955245, 2018). "Notably, our recent in vitro study demonstrated that hypoxia could induce PlGF overexpression dependent on HIF-1α during liver fibrosis, then promotes HSCs activation and proliferation through modulating PI3K/Akt signaling pathway." (PMID 28744285, 2017). "Furthermore, we hypothesized that knockout of HIF-1α in the hepatocyte—by use of a Cre-recombinase system tied to an albumin promoter—would reduce liver fibrosis in our model." (PMID 28030556, 2016). "Our results provide evidence that curcumin could protect against CCl4-induced liver fibrosis by inhibiting HIF-1α through the ERK-dependent pathway, indicating that HIF-1α might be a potential target and curcumin might be an attractive agent for treatment of liver fibrosis." (PMID 25407718, 2014). "Therefore, the purpose of the present study was to investigate whether curcumin could act as anti-liver fibrosis agent through regulation of ERK/HIF-1α in liver fibrosis in rats induced by CCl4, a widely used chemical to induce liver injury in rodents." (PMID 25407718, 2014). "In liver fibrosis, the Gly28 residue of lactate dehydrogenase A (LDHA) binds to HIF-1α to form a complex, which enhances the expression of glycolysis-related genes, thereby promoting aerobic glycolytic reprogramming during HSC activation." (PMID 40421024, 2025).
liver fibrosis (continued). "To this aim, we used an experimental model of thioacetamide (TAA)-induced liver fibrosis, modulating the activity of AMP-activated protein kinase (AMPK)/Sirtuin-1 (SIRT-1) and inhibiting hypoxia-inducible factor 1-alpha (HIF-1α)." (PMID 40943413, 2025). "The current study demonstrates the protective potential of Nicorandil (NIC) in alleviating liver fibrosis induced by TAA in rats, with a particular focus on the modulation of the AMPK/SIRT-1/HIF-1α signaling axis." (PMID 41365955, 2025). "This study evaluates the efficacy of NIC in attenuating thioacetamide (TAA)-induced liver fibrosis in rats, focusing on the AMPK/SIRT-1/HIF-1α signaling pathway." (PMID 41365955, 2025). "Under hypoxic conditions, HIF-1α enhances collagen and elastin expression by targeting lysyl oxidase (LOX), thereby increasing the stiffness and stability of ECM and promoting liver fibrosis." (PMID 40242037, 2025). "HIF-1α is capable of regulating the release of lysyl oxidase (LOX), an enzyme that crosslinks extracellular matrix proteins and promotes liver fibrosis in NASH." (PMID 37850091, 2023). "Compared with normal tissues, Collagen I, α-SMA, and HIF-1α were highly overexpressed in cirrhosis tissues, and CAT expression displayed dark areas, indicating that liver fibrosis was accompanied with hypoxia and decreased CAT expression." (PMID 36797395, 2023). "Several key mediators of aerobic glycolysis, including HIF-1α and pyruvate kinase M2 (PKM2), are upregulated during steatohepatitis and liver fibrosis." (PMID 37566009, 2023). "Based on these predictions, we selected PIK3CA, AKT1, HIF1A, VEGFA, and other related targets as the candidate targets of saffron for anti-hepatic fibrosis and conducted further experimental validation." (PMID 37959658, 2023). "The research results prove that saffron has a therapeutic effect on liver fibrosis, and its mechanism of action is related to the regulation of the AKT/HIF-1α/VEGF signaling pathway." (PMID 37959658, 2023). "For example, paeoniflorin inhibits HIF-1α translation by mTOR and attenuates CCL4-induced liver fibrosis in rats." (PMID 35682354, 2022). "It mainly enhances the autophagy process via HIF-1α and activates HSC during liver fibrosis via PI3K/AKT signaling pathway." (PMID 35681439, 2022). "Knockout of myeloid HIF1α inhibits the expression of PDGF, α-SMA and Col1A1 induced by BDL, and significantly mitigates the progression of liver fibrosis." (PMID 34853322, 2021). "Recent studies have shown that hypoxia in liver tissue accompanying or artificially induced during the progression of liver fibrosis upregulates vascular endothelial growth factor (VEGF) in HSCs and LSECs through its effector molecule HIF-1α." (PMID 33933107, 2021). "Liver fibrosis/hepatic stellate cell activation, LXR/RXR activation, FXR/RXR activation, atherosclerosis signaling, NRF2-mediated oxidation stress response, HIF1α signaling, and gap junction signaling were enriched." (PMID 33505467, 2021). "Over-expression Erk1 significantly enhanced the activity of HIF1α under hypoxia, HIF1α and Erk expression increased with CCL4-induced rat liver fibrosis." (PMID 34853322, 2021). "Glutamine metabolism was mediated by liver fibrosis related signal transduction pathway, such as TGF-β, hedgehog (Hh), hypoxia-inducible factor 1α (HIF-1α) and wnt signaling pathways." (PMID 34627378, 2021). "Several important signaling pathways, such as mTOR/HIF-1α, TGF-β1/Smads, and JAK2/STAT6, are involved in the effect of paeoniflorin on activated HSC and ECM inhibition during liver fibrosis." (PMID 32410996, 2020). "Our study disclosed the protective role miR-98 played in liver fibrosis by targeting HLF and regulating a novel HIF-1α/TGF-β/Smad2/3 signaling pathway." (PMID 32637414, 2020).
liver fibrosis (continued). "However, further investigations are needed to evaluate whether the increase in both expressions is oxygen-dependent or if there is an independent mechanism where HIF-1α, along with purinergic signaling, can contribute to the onset and development of liver fibrosis." (PMID 32225112, 2020). "The aim of the study was to evaluate the mechanisms of HIF-1α inhibitor, YC-1, during bile duct ligation (BDL)-induced liver fibrosis in mice." (PMID 29156788, 2017). "Our results indicate that HIF-1α and HIF-2α play different roles depending on the aetiology of liver fibrosis." (PMID 28112200, 2017). "To confirm the involvement of HIF-1α and HIF-2α in the regulation of liver fibrosis in BDL- and CCl4-treated mice, we silenced HIF-1α, HIF-2α, or both in vivo." (PMID 28112200, 2017). "Moreover, string analysis revealed that HIF-1α (Hypoxia-inducible factor 1-alpha), one of the interacting partners of HBx (Hepatitis B X protein), may play a role in the altered glycolytic response and oxidative stress observed in liver fibrosis." (PMID 28439208, 2016). "CDCA also reduced hypoxic induction of other HIF-1α target genes such as lysyl oxidase (LOX) and collagen prolyl-4 hydroxylase A1 (P4HA1) which are involved in hepatic fibrosis." (PMID 26098428, 2015). "A recent report indicated there are increased levels of HIF-1α and TGF-β1 in peripheral blood mononuclear cells (PBMCs) and serum in HIV-infected individuals, and the upregulation of HIF-1α contributes to TGF-β-mediated HBV-induced liver fibrosis." (PMID 41375167, 2025). "Therefore, the current study aims to investigate the therapeutic potential of NIC in TAA-induced liver fibrosis in rats, focusing on its ability to regulate the AMPK/SIRT-1/HIF-1α axis and promote liver regeneration." (PMID 41365955, 2025). "Additionally, HIF-1α interacts with key pathways—including PI3K/AKT/mTOR, MAPK/ERK, and NF-κB—all of which contribute to the onset and progression of liver fibrosis." (PMID 40791591, 2025). "Therefore, the goal of the present study was to assess the role of RUP in DEN-induced liver fibrosis and its actions on PAF/NF-κB p65/TGF-β1 and Hh/HIF-1α/VEGF signaling pathways." (PMID 36811777, 2023). "RT-PCR and Western blotting analysis confirmed that saffron treatment can prevent the CCl4-induced upregulation of HIF-1α, VEGFA, AKT, and PI3K, suggesting that saffron may regulate AKT/HIF-1α/VEGF and alleviate liver fibrosis." (PMID 37959658, 2023). "What’s more, H2O2 and HIF-1α could further stimulate the upregulation of TGF-β1, which set up a vicious cycle and acted as a difficult barrier for liver fibrosis treatment." (PMID 36797395, 2023). "More importantly, RUP inhibited liver fibrosis not only through suppression of HSCs activation and ECM deposition but also through Hh pathway impediment as well as its anti-angiogenic effect via inhibition of HIF-1α/VEGF trajectory." (PMID 36811777, 2023). "Conversely, in hepatocyte-specific HIF-1α deficient mice when only CCL4 treatment was given, liver fibrosis did not reduce." (PMID 36523459, 2022). "Some researchers found HIF-1α/SLC7A11 pathway affected liver fibrosis through the mechanism of ferroptosis, but they did not explore the regulatory mechanism." (PMID 36439690, 2022). "Hsu also found that green tea polyphenols by inhibiting the expression of HIF-1α, Akt signaling pathway and its downstream target gene VEGF, significantly improve intrahepatic vascular proliferation, liver fibrosis and portosystemic shunt in BDL (bile duct ligation) rats." (PMID 33933107, 2021). "In addition, targeting HIF1α in hepatocytes and HSC has also been shown to regulate the occurrence of liver fibrosis in different experimental induction models." (PMID 34853322, 2021).
liver fibrosis (continued). "Our studies based on chronic CCL4, bile duct ligation, and subacute TAA mouse models show that SYK in monocyte-derived macrophages (MoMFs) is fully dependent on phosphorylation of Erk to up-regulate the expression of Hif1α, thereby forming the crosstalk with SYK to drive liver fibrosis progress." (PMID 34853322, 2021). "Collectively, our study demonstrates that miR-98 suppress HSCs activation by targeting HLF directly and interacting with HIF-1α/TGF-β/Smad2/3 signaling pathway, which may be an effective therapeutic target for liver fibrosis." (PMID 32637414, 2020). "Liver fibrosis in HCC, along with excess consumption of oxygen by hepatocytes, leads to tissue hypoxia, and the survival of cells becomes dependent on expression of HIF-1α." (PMID 30575816, 2019). "In conclusion, the anti-liver fibrosis effect of GGCLT, which suppresses hepatic oxidative stress and angiogenesis, may be dependent on an HIF-1α-mediated pathway." (PMID 31455001, 2019). "In conclusion, we confirmed that PB2 inhibited the Hh signalling pathway and therefore down‐regulated the transcription of VEGF‐A, HIF‐1α, α‐SMA, Col‐1 and TGF‐β1 in HSCs to suppress activation, ECM production and angiogenesis, thus reversing the progression of liver fibrosis." (PMID 31328391, 2019). "Based on our findings, we suggest that the possible mechanisms of the anti-liver fibrosis effect of GGCLT (i.e., suppression of hepatic oxidative stress and angiogenesis) may be dependent on an HIF-1α-mediated pathway." (PMID 31455001, 2019). "The function of HIF-1α in the development of liver fibrosis has certified by the experiments used in HIF-1α liver-conditional knockout mice, which suggested that HIF-1α-recruitment preceded fibrosis and that the silencing of HIF-1α led to a remarkable decrease of ECM deposition in hepatocyte." (PMID 29862292, 2018). "An increasing expression of HIF-1α and ERK accompanies CCl4-induced liver fibrosis in rats." (PMID 25407718, 2014). "Of note, mice with endothelial-specific deletion of HIF-1α appeared normal under physiological conditions although it remains to be determined whether these mice would phenocopy the BRG1 ecKO mice with regard to liver fibrosis as reported here." (PMID 32478075, 2020). "In the CCl4 groups, the effect of HIF-2α silencing in attenuating liver fibrosis was significantly higher compared with the effect of silencing HIF-1α, however, silencing HIF-1α plus HIF-2α did not achieve a greater attenuation of fibrosis than silencing HIF-2α alone (p = 0.280)." (PMID 28112200, 2017). "In addition, silencing HIF-1α plus HIF-2α was significantly weaker at inhibiting fibrosis compared with VHL overexpression, indicating that there may be an HIF-1α- and HIF-2α-independent pathway for VHL to attenuate liver fibrosis." (PMID 28112200, 2017). "However, there is no study on the role of the ERK/HIF-1α pathway in liver fibrosis treated with curcumin." (PMID 25407718, 2014). "However, the link between CIH and fibrosis may not always be HIF1α mediated, as, while HIF1α deletion improved liver fibrosis and inflammation in trans-fat diet fed mice with or without CIH, it did so without significant interaction with CIH effects." (PMID 34692739, 2021). "Similarly, we also demonstrated that HIF‐1α was increased in fibrotic livers in vivo, which was consistent with previous reports 5, 6; however, PlGF‐specific siRNA inhibited the expression of HIF‐1α in fibrotic livers, thus leading to the decreased liver fibrosis and angiogenesis." (PMID 28378526, 2017). "Interestingly, when VHL and HIF-1α or HIF-2α were both overexpressed, HIF-1α and HIF-2α were equally effective at preventing the inhibitory effect of VHL on liver fibrosis, and the dominant effect of HIF-2α in toxic liver fibrosis did not exist." (PMID 28112200, 2017).
bladder cancer (107 papers, 2006 to 2026). "A significant positive association was found between ZEB1 and HIF-1α protein expression in bladder cancer." (PMID 37627900, 2023). "HIF-1α is often overexpressed in cancer, and the expression level is associated with poor outcomes in several types of cancer, including bladder cancer." (PMID 37086261, 2023). "Resistance to cisplatin in BIU-87 bladder cancer cells under hypoxic conditions can be explained by activation of autophagy, which is regulated by HIF-1α-associated signaling pathways." (PMID 33681390, 2021). "High HIF1α expression is associated with mortality from cancers of the bladder, brain, breast, colon, cervix, endometrium, head and neck, lung, ovary, pancreas, prostrate, rectum and stomach." (PMID 26743088, 2016). "The association between HIF-1α and STn overexpressions and tumour invasion was further confirmed in bladder cancer patient samples." (PMID 27542232, 2016). "We next investigate whether activation of PI3K/AKT and HIF-1α is implicated in Vitamin K2-upregulated glycolysis in bladder cancer cells." (PMID 32382009, 2020). "In this study, we demonstrated that AE-AS inhibits the angiogenesis in bladder cancer in vitro and in vivo, which may be associated with inhibition of HIF-1α-mediated responses." (PMID 28710377, 2017). "The results showed that under hypoxic conditions, knockdown of HIF-1α enhanced bladder cancer cell proliferation, migration, invasion, and angiogenesis while suppressing apoptosis." (PMID 41680285, 2026). "YBX1 regulates the expression of c-Myc and HIF1α in bladder cancer, further upregulating glycolytic enzymes to promote glycolysis, but the role of YBX1 in regulating glycolysis in kidney cancer has not been reported." (PMID 41507134, 2026). "This study aimed to investigate the effects of HIF-1α knockdown on bladder cancer cell proliferation, apoptosis, migration, invasion, and angiogenesis." (PMID 41680285, 2026). "Analysis of clinical samples revealed that HIF-1α levels were significantly elevated in bladder cancer tissues." (PMID 41680285, 2026). "Hypoxia-inducible factor 1α (HIF-1α) plays a central role in enabling tumor cells to adapt to hypoxic conditions; however, its specific mechanisms of action in bladder cancer remain incompletely understood." (PMID 41680285, 2026). "A previous study has established a correlation between the hypoxia-related HIF-1α signaling pathway and the development of bladder cancer." (PMID 38806990, 2025). "For example, FGFR3 expression was elevated in hypoxia and HIF-1α-dependent manners in bladder cancer." (PMID 38542288, 2024). "An upregulation of another reader, ALYREF, under the HIF1A control, contributes to enhanced glucose metabolism in bladder cancer." (PMID 39164641, 2024). "For instance, bladder cancer cells can re-educate M2 TAMs through lactate secretion, activating HIF-1α to promote TGF-β secretion." (PMID 38840205, 2024). "Immunohistochemical studies utilizing a monoclonal antibody specific for HIF-1α have shown that the most common types of human cancer, including bladder cancer, exhibit upregulation of HIF-1α." (PMID 38602556, 2024). "The present study provides the first evidence demonstrating that melatonin reduces tumor growth through the suppression of the HIF-1α and NF-κB pathways in bladder cancer cell lines." (PMID 37086261, 2023). "JMJD1A promotes the transcription of PGK1 by regulating H3K9me2 levels in the PGK1 promoter region and interacting with HIF-1α to regulate the glucose metabolism pathway in bladder cancer cells, thus regulating the progression of bladder carcinoma." (PMID 37394582, 2023). "The ellagic acid has been reported to have HIF-1α suppressive effects on the human urinary bladder carcinoma cell line (ECV304)." (PMID 38187496, 2023). "In bladder cancer, it promotes tumor development and metabolic reprogramming through the HIF-1α pathway." (PMID 37153789, 2023).